PYY (peptide YY)
Diseases named in the same sentence as PYY in open-access papers (continued):
Sharing a sentence is not in itself a finding about the gene and the disease.
Obesity (continued). "Moreover, this new generation probiotic significantly upregulated the expression of two important gut hormone genes, GLP-1 and PYY, involved in the appetite suppressing and anti-diabetic plus anti-obesity properties, respectively." (PMID 34065217, 2021). "In obesity, circulating levels of PYY and GLP-1 are decreased." (PMID 33924402, 2021). "Altered production or action of gut hormones, including glucagon-like peptide-1 (GLP-1), glucose-dependent insulinotropic polypeptide (GIP) and peptide YY (PYY), may contribute to the biological basis of obesity and altered glucose homeostasis." (PMID 33175577, 2021). "Therefore, the anorectic effects of PYY, and the potential to stimulate reproductive hormone release, would be advantageous in the treatment of obesity with coexisting hypogonadism." (PMID 31628465, 2020). "Unlike leptin and insulin, obesity does not seem to cause peripheral resistance to PYY, suggesting that the observed increases in older adults are likely to exert anorectic effects." (PMID 31432431, 2020). "We also found a possible mechanism of CAP’s anti-obesity effect by enhancing PYY and GLP-1excretion in intestinal epithelial cells, which suppress NPY- and AgRP-expressing neurons and activate POMC- and CART-expressing neurons in the ARC of the hypothalamus, resulting in lower food intake." (PMID 32180694, 2020). "Nevertheless, understanding the precise mechanisms in the interaction between bacteria and PYY could lead to developing novel therapeutic strategies to prevent or treat obesity." (PMID 30837951, 2019). "As the breastfed infants had higher PYY levels, that could be a link in the protective role of breastfeeding for obesity." (PMID 27170102, 2017). "While PP and PYY both present promising routes for the treatment of obesity, PP may be preferred as it inhibits feeding in mice more than PYY and PYY-3-36." (PMID 27294784, 2016). "Moreover, the role of PYY in obesity per se is contradictory: On the one hand, PYY has anorexigenic effects that counteract obesity; on the other hand, it slows down gut transit time." (PMID 27058556, 2016). "Circulating PYY levels are drastically reduced in obesity and T2D." (PMID 27117413, 2016). "Studies related to gut and adipose tissue hormones and obesity suggest that obesity is associated with a blunted postprandial response of satiety factors such as GLP-1 and PYY, CCK and reduced postprandial suppression of orexigenic ghrelin, and some type of central leptin resistance." (PMID 26499438, 2016). "Transgenic mice with increased circulating PYY are resistant to diet-induced obesity." (PMID 24778627, 2014). "Peripheral infusion of PYY reduces food intake in rodents, and transgenic mice overexpressing PYY have increased plasma PYY concentrations, and are protected against diet-induced obesity." (PMID 24675731, 2014). "However, the involvement of PYY in the development of human obesity is unclear, the relationship between circulating PYY and adiposity is controversial, and very little data exists from large human population-based studies." (PMID 24743402, 2014). "Since PYY dysfunction in obesity reflects hormone deficiency rather than hormone resistance, PYY hormone supplementation is viewed as a potential anti-obesity agent." (PMID 26237477, 2014). "One major finding for the present study is that serum PYY is not negatively associated with obesity status defined by BMI or %BF adjusting for age, sex, smoking, medication use, and menopause." (PMID 24743402, 2014). "Taken together, obesity may bias the PYY sensitivity issue, and the anorectic effect of PYY could serve as a therapeutic mechanism for developing anti-obesity drugs." (PMID 25412152, 2014). "The retained responsiveness of obese subjects to the effects of PYY-36 suggests that targeting the PYY system by alteration of the microbiome may offer a therapeutic strategy to help treat obesity." (PMID 24778627, 2014).
Obesity (continued). "Modulating PYY activity is already being investigated as a treatment for obesity." (PMID 23358528, 2013). "Also, post-prandial PYY response is known to be blunted in obese persons, and the fact that the normal-weight TE group in our study shows this pattern could be interpreted as supporting the higher prevalence and risk for obesity found in the TE type in previous studies." (PMID 22889232, 2012). "Also, PYY-null mice (unable to produce the hormone because the gene for PYY has been knocked out) are hyperphagic and develop marked obesity but are hypersensitive to exogenous PYY." (PMID 17530919, 2007). "We conclude that, in males with obesity, intraduodenal calcium, when administered alone, stimulates GLP-1 and PYY secretion and pyloric pressures and enhances the effects of Trp to stimulate CCK, GLP-1, and PYY secretion, associated with greater suppression of energy intake." (PMID 39785828, 2025). "Therefore, the authors indicate that PYY could be a promising method for treating obesity and type 2 diabetes." (PMID 39408213, 2024). "Therefore, this hormone should undergo further clinical studies, particularly involving individuals with obesity, to determine whether PYY may affect fat content and, consequently, the development of obesity and its complications." (PMID 39408213, 2024). "However, the lower ghrelin plasma concentrations, both in the fasting and postprandial states, and lower postprandially PYY secretion seen in individuals with obesity, questions this hypothesis and asks for more research." (PMID 36416279, 2023). "The meta‐analysis showed that individuals with obesity indeed present with statistical significantly lower basal and postprandial total ghrelin concentrations compared with controls, lower postprandial concentrations of total PYY, and lower postprandial hunger ratings." (PMID 36416279, 2023). "As an effective therapeutic option for both obesity and DM, bariatric surgeries are beneficial far beyond contributing to weight loss but also recovering islet function by reversing metabolic disorders and normalizing the levels of glucagon-like peptide 1 (GLP-1) and peptide YY (PYY)." (PMID 37152942, 2023). "At present, more compounds of receptors with dual agonists are being tested, for example, GLP-1R/GR (glucagon receptor), GLP-1R/AR (amylin receptor) and GLP-1R/NPYR (peptide YY binds to neuropeptide Y receptors), and might achieve further advances in T2DM, obesity and associated conditions therapy." (PMID 37904255, 2023). "In the comparison of AUC, the pooled SMDs for total ghrelin, active GLP‐1 and total PYY also indicated lower postprandial concentrations in the obesity group, with the AUCs for both total ghrelin and total PYY being statistically significantly smaller in obesity (respectively)." (PMID 36416279, 2023). "This suggests that PYY may be involved in the pathophysiology of obesity." (PMID 37600709, 2023). "In addition to stimulating GLP-1 secretion in vitro and in vivo, we found that EA also greatly increased circulating PYY in mice and directly stimulated PYY release from cultured L-cells, which should be a major contributing factor for the hypophagic and anti-obesity effects of EA treatment." (PMID 36386896, 2022). "Therefore, agents that are capable of targeting both GLP-1 and PYY secretion could be a safe and effective strategy in the prevention and treatment of T2D by promoting obesity and insulin resistance control and simultaneously improving functional β-cell mass." (PMID 36386896, 2022). "Our finding of an increase in postprandial PYY after prolonged HYPOXIA concomitant with a reduction of spontaneous energy intake could support the notion of a potentially beneficial role of hypoxia in obesity prevention." (PMID 35095562, 2021). "Finally, we assessed the impact of obesity on MUFA vs. SFA-mediated PYY production in mice." (PMID 32397573, 2020).
Obesity (continued). "Alongside the well-established anti-diabetic and lipid-lowering properties, preclinical studies also suggest that glucans may exert anti-obesity effects by activating the gut-hypothalamic (Peptide YY- Neuropetide Y) axis, therefore increasing satiety in diet-induced obese mice." (PMID 32962190, 2020). "Therefore, augmenting PYY levels may have a positive impact on improving insulin tolerance in obesity related comorbidities." (PMID 30837951, 2019). "Consequently, PYY analogues are currently under investigation for the treatment of obesity." (PMID 31306808, 2019). "Thus, gut hormones (e.g., GLP-1 and PYY) can contribute to weight management that might eventually halt the development of obesity." (PMID 28323997, 2017). "However, many successive PYY knockout studies have failed to reproduce the strong association of PYY with hyperphegia and diet-induced obesity." (PMID 24743402, 2014). "Establishing the full repertoire of Gpr119-activated intestinal mechanisms that enhance not only GLP-1 but also PYY-mediated responses with consequent antihyperglycemic effects now provides an optimal platform for a high-affinity Gpr119 agonist to treat diabetes and obesity." (PMID 20519124, 2010). "Moreover, chronic treatment with PYY reverses their obesity phenotype." (PMID 17530919, 2007). "Obesity is linked to altered secretion of anorexigenic gastrointestinal hormones, such as glucagon-like peptide 1 (GLP-1) and peptide YY (PYY), whose levels can be decreased or enhanced likely depending on the prandial phase and obesity progression." (PMID 41566927, 2026). "Activation of free fatty acid receptor 2 (FFAR2) on enteroendocrine L-cells mediates secretion of glucagon-like peptide 1 (GLP-1) and peptide YY (PYY), key regulators of central appetite control with therapeutic relevance to obesity." (PMID 41844830, 2026). "Individuals with overweight or obesity often exhibit altered fasting and postprandial levels of hormones such as ghrelin, GLP-1, and PYY compared with normal-weight individuals." (PMID 40806130, 2025). "Specifically, fasting levels of PYY and GLP-1 are often reduced in individuals with obesity compared with those with normal body weight, while their postprandial secretion is also blunted." (PMID 40806130, 2025). "Conversely, ACSL5 knockdown reduces food intake by increasing glucagon-like peptide (GLP) and peptide YY (PYY) secretion and decreasing gastric emptying rate, mitigating HFD-induced obesity and insulin resistance." (PMID 41288931, 2025). "Previous research suggests that GUDCA administration improves obesity and glucolipid metabolism, while TCA stimulates secretion of glucagon-like peptide-1(GLP-1) and peptide YY (PYY), enhances satiety, and improves insulin sensitivity." (PMID 41306672, 2025). "In contrast to PYY, GLP-1 has been evaluated extensively in large clinical studies and serves as the foundation for several approved treatments for T2D and obesity, such as liraglutide and semaglutide." (PMID 41228539, 2025). "There is no consensus that fasting GLP-1 concentrations are altered in obesity, although the postprandial increase in GLP-1 is attenuated as observed for PYY." (PMID 41043686, 2025). "Although PYY levels are negatively correlated with adiposity, PYY sensitivity appears preserved in the context of obesity or HFD feeding, and exogenous PYY attenuates obesity-related inflammation in WAT." (PMID 40723884, 2025). "Conversely, in individuals with overweight or obesity, HIIE protocols appear to produce similar responses in suppressing AG and subjective appetite perceptions whilst elevating GLP-1 and PYY compared to CME." (PMID 40425789, 2025). "Compared with individuals with normal weight individuals with obesity have been found to have attenuated postprandial secretions of GLP-1 and PYY." (PMID 39792913, 2025).
Obesity (continued). "A substantial and growing body of preclinical evidence has examined the metabolic actions of PYY, particularly the PYY3–36 isoform, in rodent models of obesity and insulin resistance." (PMID 41228539, 2025). "These functions make PYY and GLP-1 attractive therapeutic molecules for conditions such as diabetes and obesity." (PMID 41048045, 2025). "Obesity results in lower concentrations of GLP-1, PYY, and ghrelin, whereas insulin and glucagon are increased." (PMID 41043686, 2025). "In this study, supplementation of MN-Gup-GOS-XOS increased the levels of PYY, CCK, and OXM in individuals with obesity, which provided a possible explanation for the mechanism of MN-Gup-GOS-XOS reducing LDL-C." (PMID 39664910, 2024). "Co-treatment with long acting PYY and the GLP-1 receptor agonists has potential as an efficient obesity treatment." (PMID 39183855, 2024). "Butyric acid can promote the release of gastrointestinal peptide hormones such as peptide YY (PYY) and glucagon-like peptide-1 (GLP-1), thus improving obesity and insulin sensitivity induced by a high-fat diet." (PMID 38257160, 2024). "Synbiotics supplementation significantly decreased body fat percentage, waist, and serum low-density lipoprotein cholesterol (LDL-C), increased peptide YY, cholecystokinin, oxyntomodulin, GSH (glutathione peroxidase) in individuals with obesity." (PMID 39664910, 2024). "This randomized, double-blind clinical trial showed that daily supplementation of the synbiotics MN-Gup-GOS-XOS for 12 weeks reduced body fat percentage, waist, serum LDL-C, and increased PYY, CCK, OXM, GSH in individuals with obesity." (PMID 39664910, 2024). "Ghrelin, PYY, CCK, and amylin have promising prospects for novel pharmaceutical interventions in appetite regulation and obesity treatment." (PMID 39016695, 2024). "A synthetic Novo Nordisk's PYY analogue, PYY1875/NNC0165‐1875 (NN9775‐4708), was examined in combination with semaglutide for obesity treatment but was recently discontinued following the completion of Phase II trials." (PMID 39016695, 2024). "Ghrelin, peptide YY (PYY), cholecystokinin (CCK), and amylin are crucial in appetite regulation offering promising targets for pharmacological interventions in obesity treatment using both peptide‐based and small molecule‐based pharmaceuticals." (PMID 39016695, 2024). "This study introduces the expression profile of RGS in human EECs, alterations in obesity, and suggests a role for RGS proteins as modulators of GLP-1 and PYY secretion from intestinal EECs." (PMID 39142076, 2024). "The principal finding is that Ramadan fasting has a beneficial effect on gut hormone levels for leptin, glucagon-like peptide-1 (GLP-1), peptide YY (PYY), and cholecystokinin (CCK) in males with obesity." (PMID 37139278, 2023). "Previous studies have suggested the implication of obesity with the reduced post-prandial response of glucagon-like peptide-1 (GLP-1), cholecystokinin (CCK), and peptide YY (PYY), as well as the unleashed post-prandial reaction of ghrelin." (PMID 36834794, 2023). "SCFAs were absorbed by the gut and release more gut hormones, such as glucagon-like peptide-1 (GLP-1) and peptide YY (PYY), resulting in lower food intake, thereby curbing obesity." (PMID 36545204, 2022). "Acetate, butyrate and propionate have been broadly described as beneficial gut-derived metabolites in the context of obesity for their impact on food intake through the release of satiation gut peptides GLP-1 and PYY." (PMID 35958993, 2022). "In overweight human individuals, propionate supplementation also showed anti-obesity effects by increasing postprandial GLP-1 and PYY release and reducing energy intake." (PMID 35629921, 2022). "Other SCFAs such as butyrate and propionate protected against diet-induced obesity and regulated gut hormones such as glucagon-like peptide-1, glucose-dependent insulinotropic polypeptide (GIP), peptide YY, and ghrelin." (PMID 35126309, 2021).
Obesity (continued). "Obesity is a multifaceted disease where intestinal hormones such as cholecystokinin (CCK), glucagon-like peptide 1 (GLP-1), and peptide YY (PYY), produced by enteroendocrine cells (EECs), have a pivotal role as signaling systems." (PMID 33669189, 2021). "Conversely, accumulating evidence showed that SCFAs act through GPR41 and GPR43 in L cells to promote peptide YY (PYY) and GLP-1 and alter satiety and energy intake, which further alleviates obesity or NAFLD indirectly." (PMID 34660662, 2021). "This study investigated the effects of RIF on gut hormones (leptin, ghrelin, GLP-1, PYY, and CCK) in males with obesity in Tunisia." (PMID 32756479, 2020). "We studied the effects of Ramadan intermittent fasting (RIF) on gut hormones (leptin, glucagon-like peptide-1 (GLP-1), peptide YY (PYY), cholecystokinin (CCK), and ghrelin) in males with obesity." (PMID 32756479, 2020). "The related genes of obesity (ADIPOQ, GCG, PCSK1N, TFAP2A, and PYY) were also found to play significant roles in the occurrence of some types of cancer (BRCA, COAD, and UCEC)." (PMID 33299884, 2020). "Particularly, a role for butyrate was described in the prevention of obesity by regulating incretins and anorexigenic hormones production (GLP-1 and peptide YY), appetite and energy expenditure." (PMID 33292434, 2020). "Another configuration of a disposable immunosensing platform for the simultaneous determination of two obesity-related hormones, ghrelin (GHRL) and peptide YY (PYY) was also reported by this group." (PMID 29495294, 2018). "The treatment of obesity and type 2 diabetes with metabolic surgery influences the physiological role of incretins like GLP-1, GIP, and PYY, which are important players in glucose homeostasis improvement." (PMID 28840471, 2018). "Thus, PYY replacement may be used to treat overweight and obesity." (PMID 25412152, 2014). "The combination of peptide YY (PYY) and glucagon-like peptide-1 (GLP-1) has been proposed as a potential treatment for diabetes and obesity." (PMID 25144632, 2014). "As a result, analogs of PYY and GLP-1 are being developed as treatments for obesity and diabetes, although the doses that can be given are limited by adverse effects, principally nausea." (PMID 25144632, 2014). "In conclusion, only a few studies so far have evaluated the effect of weight reduction on (postprandial) PYY, GLP-1, or ghrelin concentrations in children with obesity." (PMID 22363876, 2011). "Promisingly, anorectic gut hormones, including peptide YY (PYY) and glucagon-like peptide 1 (GLP-1), have recently emerged as potential therapeutic targets for obesity." (PMID 22000927, 2011). "There does not appear to be resistance to PYY action in individuals with obesity, as exogenous administration led to appetite suppression similar to that observed in healthy controls." (PMID 41575482, 2026). "Bariatric surgery emerges as the most effective long-term intervention for obesity, not only through anatomical changes but also by inducing favorable hormonal shifts—particularly increased levels of GLP-1 and PYY—that enhance satiety and improve glucose metabolism." (PMID 41150735, 2025). "The contribution of PYY and CCK to obesity remains unclear as some studies report inconsistent hormone levels pre- and post-meal in individuals with obesity." (PMID 41441026, 2025). "Multiple clinical studies have investigated PYY’s involvement in glucose metabolism, appetite regulation, and insulin sensitivity among individuals with and without obesity or T2D." (PMID 41228539, 2025). "Pharmacologic GLP-1RA administration has been shown to have various reductions in food consumption scores and an increase in perceived fullness in humans with obesity, where postprandial plasma levels of GLP-1 decreased and peptide YY (PYY) levels increased with the GLP-1RA liraglutide." (PMID 40722684, 2025).